SMPD3 (sphingomyelin phosphodiesterase 3)
Diseases named in the same sentence as SMPD3 in open-access papers (continued):
Sharing a sentence is not in itself a finding about the gene and the disease.
tumor (continued). "We aim to understand how SMPD3 expression influences HCC cell proliferation, apoptosis, and tumor growth." (PMID 40226357, 2025). "In vitro and in vivo experiments were conducted to evaluate the effects of SMPD3 overexpression on HCC cell lines and tumor growth in mice." (PMID 40226357, 2025). "In vitro and in vivo experiments demonstrated that SMPD3 overexpression significantly decreased HCC cell proliferation, migration, and invasion and inhibited tumor growth in a nude mouse model." (PMID 40226357, 2025). "Our data is consistent with a previous study reporting the antiproliferation role of SMPD3 in HCC cell line and can also regulate tumor cell migration." (PMID 40226357, 2025). "In PD-L1 antibody-resistant tumor tissues, cancer cell growth is inhibited by removing exoPD-L1 by knocking out RAB27A (member RAS oncogene family) and NSMASE2 (sphingomyelin phosphodiesterase 3)." (PMID 35990664, 2022). "Neutral sphingomyelinase-2 (SMPD3), which is a target of an inhibitor of EV-release GW4869, enhances TEV release from tumor cells." (PMID 34751648, 2021). "The authors identified 13 tumor suppressor genes, of which two (neurofilament heavy polypeptide, NEFH and sphingomyelin phosphodiesterase 3, SMPD3) were functionally validated in vivo." (PMID 31056726, 2019). "SMPD3, which is down regulated uniquely in CPA/6d-treated GL261(scid) tumors, can promote angiogenesis within the tumor microenvironment as well as metastasis by regulating exosomal microRNA secretion." (PMID 27515027, 2016). "In vitro experiments demonstrated that SMPD3 overexpression in HCC cell lines significantly reduced cell proliferation, migration, and invasion, while in vivo experiments in nude mice showed that SMPD3 overexpression inhibited tumor growth." (PMID 40226357, 2025). "Furthermore, some studies have suggested that SMPD3 may impact key signaling pathways, such as the MAPK/ERK pathway, which are known to play a crucial role in tumor growth and metastasis." (PMID 40226357, 2025).
cancer (39 papers, 2013 to 2026). A tumor composed of atypical neoplastic, often pleomorphic cells that invade other tissues. "Meanwhile, recent studies implicated that SMPD3 may help modulate immunotherapeutic efficiency in various cancers." (PMID 40226357, 2025). "Sphingomyelin phosphodiesterase 3 (SMPD3) has recently been suggested to play an antitumor role in several cancers." (PMID 40226357, 2025). "In summary, we have identified the promoter region of SMPD3 as a common site of hypermethylation and downregulation in oral tumors and in oral dysplasia and cancer cell lines." (PMID 32082486, 2020). "SMPD3 expression has been shown to alter radiosensitivity in other cancer types and radiation is commonly used to treat OSCC." (PMID 32082486, 2020). "To further elucidate the role of SMPD3 in oral dysplasia and cancer, we overexpressed the gene in oral dysplasia (DOK) and carcinoma (SCC-25) cell lines using a doxycycline-inducible vector." (PMID 32082486, 2020). "Taken together, our results suggest that promoter hypermethylation and silencing of SMPD3 are common events in oral tumorigenesis and that they occur early on in cancer progression (i.e., dysplasia)." (PMID 32082486, 2020). "The SMPD3 gene plays a key role in cancer, particularly in the lipid remodeling of cancer cells." (PMID 41262533, 2026). "Recent research has suggested that SMPD3 might have a role in modulating cell cycle regulation, inducing apoptosis, and inhibiting cancer cell proliferation." (PMID 40226357, 2025). "In addition, there is a possibility that the inhibition of SMPD3 blocks the cytotoxicity of tumor necrosis factor (TNF) in cancer cells." (PMID 32756339, 2020). "Thus, it appears as though hypermethylation is the primary mechanism underlying SMPD3 deregulation in OSCC and possibly other cancer types." (PMID 32082486, 2020). "Current studies on the roles of HMOX2 and SMPD3 in AML are largely blank, but they play important roles in other cancers, so more preliminary single-gene bioinformatics analyses are needed." (PMID 33117716, 2020). "For non-cancer studies, the miDRB-targeted exosome biogenesis genes for ferroptosis-inhibiting miRNAs are retrieved as follows: miR-19a-3p (SDC1, VPS4B, and MYO5B), miR-424-5p (VPS4A and MYO5B), miR-4291 (ATP9A, SMPD3, TSG101, and MYO5B), miR-522-3p (PDCD6IP), and miR-670-3p (CD34 and RAB27A)." (PMID 38892270, 2024).
metabolic disease (2 papers, 2021 to 2025). A congenital disorder (due to inherited enzyme abnormality) or acquired (due to failure of a metabolically important organ) disorder resulting from an abnormal metabolic process. "Consistent with the clinical observation that subjects with PDC tend to develop a metabolic disorder, series-clustering analysis detected several key lipid metabolic genes (PRKAR1A, ACSL4, SMPD3, etc.)." (PMID 34926685, 2021).
SMPD3 also shares sentences with these, for which no sentence is quoted: infection (7 papers); leukemia (6); Obesity (5); Insulin resistance (4); neurodegenerative disease (3); brain ischemia (2); breast tumor (2); clear cell renal cell carcinoma (2); cognitive decline (2); heart failure (2); multiple sclerosis (2); osteosarcoma (2); Parkinson disease (2); pituitary hormone deficiency (2); acute leukemia (1); acute lymphocytic leukemia (1); acute myeloid leukemia (1); alcohol addiction (1); alcoholism (1); autoimmune disease (1); bladder urothelial carcinoma (1); brain inflammation (1); breast invasive carcinoma (1); calcification (1); cardiovascular diseases (1); Cerebral ischemia (1); cervical cancer (1); chronic lung disease (1); chronic obstructive pulmonary disease (1); colon adenocarcinoma (1).
A further 36 diseases each share a sentence with SMPD3 in 1 paper.